CFL1 (cofilin 1)
Diseases named in the same sentence as CFL1 in open-access papers (continued):
Sharing a sentence is not in itself a finding about the gene and the disease.
cancer (continued). "It is well known that the inhibition of LIM kinase 1 downregulated CFL1 phosphorylation, which then suppresses the motility of cancer cells." (PMID 33791303, 2021). "Treatment with anti-cancer drug induced ROS accumulation and cell death by promoted cofilin-1 translocation to mitochondria." (PMID 33901009, 2021). "Various studies in different types of cancers describe a correlation of CFL1 expression with an aggressive phenotype and worse prognosis for patients." (PMID 33578795, 2021). "Since CFL1 has previously been described to influence the migratory potential of cancer cells, we measured the influence of CFL1 knockdown on the migratory potential of cells by cell tracking and wound healing experiments." (PMID 33578795, 2021). "We also identified that miR-107 induced cancer cell death and increased chemosensitivity by targeting cofilin-1." (PMID 33901009, 2021). "CFL1 is highly expressed in endometrial cancer, and its knockdown reduces the invasive ability and matrix metalloproteinases activity in cancer cells." (PMID 33784016, 2021). "Although this mechanism is certainly applicable to a large number of cell types, some recent studies have shown that CFL1 is also involved in lamellipodia formation, which is the driving force of cancer cell migration." (PMID 33578795, 2021). "Intuitively, an increase in CFL1 expression by transfection would expect to increase the metastasis of cancer cells." (PMID 33791303, 2021). "Activated CFL1 participates in some essential biological processes of malignant tumors including proliferation, apoptosis, invasion, and chemo-resistance." (PMID 34076143, 2021). "Recently, much attention has been paid to the expression and regulation of CFL1 in malignant tumors." (PMID 33791303, 2021). "Studies indicated that the extracts and compounds from Traditional Chinese medicines suppressed the EMT, proliferation and migration of different cancer cells by inhibiting CFL1 signaling pathway in different cancer cells." (PMID 33791303, 2021). "The Epiafzelechin (CFL1) isolated from the CaLE fraction of Cassia fistula leaves induced a stronger cytotoxic potential towards the MG-63 cancer cell line with the GI50 value of 8.73 μM." (PMID 32093300, 2020). "Multiple actin-related proteins including ARPC1B, ARPC5, ACTL6A, and CFL1, which are markers for aggressive cancers, were part of the upregulated network nodes." (PMID 33317623, 2020). "With respect to the steps of EMT, which are essential for metastasis, the researchers of the present study studied a number of genes reported to have a role in EMT in different cancers, such as Claudin-1, Cofilin-1, AXL, and GAS6." (PMID 31700829, 2019). "Some studies suggest that CFL1 can influence the radiosensitivity of cells by altering DNA repair capacity and is involved in cancer cell migration, invasion, and metastasis." (PMID 31719794, 2019). "Interfering the expression of Cofilin 1 in cancer cell inhibit cell invasion by weaken the maturation and stability of invadopodia." (PMID 30858759, 2019). "ROC curves constructed todemonstrate the accuracy of sputum CFL1 in discriminating cancer patients fromcancer-free patients and healthy volunteers were 0.78 and 0.69, respectively." (PMID 29846436, 2018). "CFL1 at a cut-off value of 415.25 pg/mL showedsensitivity/specificity of 0.80/0.70 in differentiating between healthyvolunteers and cancer patients." (PMID 29846436, 2018). "The relevance of sputum CFL1 remained high even when the concentration was comparedbetween cancer patients and healthy volunteers, cancer patients and cancer-freepatients, and cancer-free patients and healthy volunteers." (PMID 29846436, 2018). "The EMT process is not only related to actin but also related to its associated proteins such as SATB1, CFL1, or Rho kinases (ROCKI and ROCKII), whose overexpression was noted in many cancer types." (PMID 29581975, 2018).
cancer (continued). "Other proteins in clusters 6 and 9, including annexin isoforms, cofilin-1, galectin-1 and coactosin-like protein, are also known to play different roles in cancers." (PMID 30440021, 2018). "The effects of Cofilin 1 on cancer development and progression therefore depend on its activation status, which is regulated by PKD 1 and TCF7L2." (PMID 29190896, 2017). "Correspondingly, the gene expression changes during cancer progression can be mediated by Cfl-1 through actin transport." (PMID 28025492, 2016). "Recent studies demonstrated that high-expression levels of cofilin-1 in many cancers correlated with invasion and metastasis, chemotherapy resistance, and poor prognosis." (PMID 27872653, 2016). "The molecular mechanisms of Cfl-1 involvement in the formation of malignant phenotype of cancer cells are still being investigated." (PMID 28025492, 2016). "Cofilin is an essential regulator of actin dynamics, and researchers have revealed that phosphorylation and inactivation of cofilin-1 was capable of blocking actin polymerization and metastasis in cancers." (PMID 26452645, 2015). "Similar to the ADF−/− CFL1−/− keratinocytes, when these cancer cells were stained with phalloidin, we observed a huge increase in F-actin in the form of cytoplasmic stress fibers in all the depleted cells." (PMID 26655907, 2015). "In this context, cofilin-1 – a small protein of 18 kDa – has been widely studied as a biomarker of a more aggressive phenotype of different types of cancer such as breast, gastrointestinal and NSCLC." (PMID 25784483, 2015). "Overexpression of PKM2 or cofilin-1 was observed in pooled carcinoma samples compared with corresponding adjacent normal samples when subjected to western blot assays, which was consistent with the observation made in 2-DE analysis." (PMID 22087286, 2011). "Taken together, the c-Myc-cofilin-1 regulatory axis would explain the mechanism of OIS promoted cancer progression, and it may be a potent target for design of treatments." (PMID 41888102, 2026). "Dephosphorylated CFL1 promotes actin turnover, lamellipodium formation, and cancer metastasis." (PMID 40149625, 2025). "Cofilin-1 influences the development of a variety of cancer cells." (PMID 38975937, 2024). "Similarly, CFL1 also contributes to the proliferation, invasion, and metastasis of malignant tumors." (PMID 38511143, 2024). "Additionally, differential protein expression analyses in PCa cell lines with varying metastatic abilities highlight cofilin-1 as a significantly distinct protein, suggesting its vital role in cancer invasion and metastasis." (PMID 39055653, 2024). "It seems that CFL1 expression also has an impact on cancer cell resistance to systemic therapy." (PMID 37371647, 2023). "Furthermore, RhoA inactivating regulator, i.e., Rho GTPase activating protein 29 (ARHGAP29), has been shown to regulate cancer cell metastasis via RhoA/LIMK/CFL-1 signal." (PMID 37193711, 2023). "Moreover, CFL1 upregulation has been perceived in many cancers, since it induces metastasis and inhibits apoptosis of cancer cells." (PMID 37464436, 2023). "Cofilin-1 is ubiquitously expressed in most cell types throughout development and adulthood, and it plays an important role in cell migration, proliferation, phagocytosis, and the development of various types of cancers." (PMID 35627108, 2022). "It is found that CFL1 is closely related to occurrence and development of certain cancers, which may be a new biomarker and treatment target for early diagnosis and prognosis." (PMID 33791303, 2021). "High expression level of cofilin 1 (CFL1) has been found in many types of cancers." (PMID 33791303, 2021). "However, our results showed that the cell migration was decreased after overexpression of CFL1, which was consistent with previous study that overexpression of CFL1 suppressed growth and invasion of cancer cells." (PMID 33791303, 2021).
cancer (continued). "Thus, to the best of our knowledge, our model is the first that captures holistically the regulation of CFL1 and its impact on cancer progression." (PMID 33578795, 2021). "While it is a biomarker for cancer, prior to this study, an association between CFL1 expression and RSV infection has not been reported." (PMID 33656056, 2021). "However, many other previous studies have already reported the oncogenic potential of CCT8 and CFL1 in various types of cancers." (PMID 34359304, 2021). "CFL1 is crucial for cytoskeleton remodeling and mitosis, but also for the maintenance of nuclear structure, the movement of chromosomes and the modulation of transcription frequently altered in cancer cells." (PMID 34381117, 2021). "We first explored the mRNA expression of MCL1, SRC, and Cofilin1 (CFL1) across cancers in the TCGA and Australian Pancreatic Genome Initiative (APGI) to identify contexts where a dual MCL-1, and SRC inhibitor strategy may be effective." (PMID 31735913, 2020). "Activation of ROCK/PTEN could induce human prostate LNCaP cancer apoptosis by mitochondrial translocation of cofilin-1." (PMID 30622602, 2018). "In addition,we found that cancer patients contain higher concentrations of sputum CFL1 comparedto cancer-free patients and healthy volunteers." (PMID 29846436, 2018). "Sputum CFL1 was also able todistinguish cancer-free patients from patients with LC." (PMID 29846436, 2018). "Furthermore, we also explored the effects of CFL-1 in HUNK-mediated cancer metastasis in vivo." (PMID 37193711, 2023). "Furthermore, docetaxel itself suppressed the expression of CFL1 in cancer cells." (PMID 37371647, 2023). "However, detailed studies into the exact role of cofilin-1 in cancer is still somewhat limited." (PMID 34678587, 2022). "Cofilin 1, the non-muscle isoform of the cofilin 1 gene product, plays a key role in cell migration and cytokinesis and is directly associated with the invasion, metastasis, and chemoresistance of various human malignant solid tumors." (PMID 29190896, 2017). "In these works, however, the relation of cofilin-1′s expression with a more aggressive phenotype of tumors was attributed to its classical activity upon actin cytoskeleton modulation, related to improved migration and invasion capacity in cancer cells, as reviewed recently." (PMID 25784483, 2015). "The remaining eight target genes (CFL1, FNBP4, NDUFB3, OCIAD2, PLIN3, POU2AF1, RAC1, TMEM141) presented a combined influence in five or fewer cancer types." (PMID 39201394, 2024). "In consistent with our study, it has been demonstrated that HUNK suppresses cancer metastasis by competitively binding to CFL-1 and protecting dephosphorylation of CFL-1 by PP2A." (PMID 37193711, 2023). "CFL1 is reported to be an over‐expressed gene in HCC, and confers chemo‐resistance in cancer cells to HDAC inhibitors." (PMID 33784016, 2021). "Cofilin-1 (CFL-1) and its modulators, LIMK1/SSH1, play key roles in mediating the invasiveness by driving actin cytoskeleton reorganization in various cancer types." (PMID 33482809, 2021). "In colorectal cancer (CRC), knockdown of CFL1 represses cell migration, invasion, and EMT in cancer cells via regulation of actin cytoskeleton organization." (PMID 33784016, 2021). "Our above discussion has shown that the expression level of most ABPs is positively correlated with proliferation and invasion of related cancer cells, except TWF1, cofilin-1, and PDLIM4." (PMID 34194957, 2021). "Altered levels of ABPs such as α-actinin, villin, filamin, formin, CFL1, Arp2/3, GLS, TAGLN, or fascin were found in many types of cancers, which correlated with poor clinical outcome." (PMID 33036298, 2020). "The cBioPortal analysis program identified 12 types of human cancer with significant CNAs in the chosen genes’ signature (CAP1, CAP2, CFL1, CFL2, DSTN)." (PMID 28423713, 2017). "Recently studies had shown that phosphorylated cofilin-1 (p-cofilin-1) and cofilin-1 played an important role in MDR of cancer." (PMID 27872653, 2016).
cancer (continued). "In vitro and in vivo assays demonstrated that knockdown of NAV2 led to reduced migration and invasion of cancer cells, and the process involved the regulation of F-actin polymerization through the SSH1L/cofilin-1 pathway." (PMID 26452645, 2015). "In this review, we will discuss the role of CFL-1, actin cytoskeleton and other AAPs on DDR, and the implication of actin targeting for cancer radiotherapy." (PMID 25689427, 2015). "In this review, we will discuss the possible involvement of CFL-1 in DNA damage responses (DDR) induced by ionizing radiation (IR), and the implications for cancer radiotherapy." (PMID 25689427, 2015). "According to the current model, the actin subunits provided by Cofilin 1-mediated actin cleavage are used by the Arp2/3 complex and by VASP to elongate F-actin at the tips of cellular protrusions and thereby drive migration and invasion of cancer cells." (PMID 39281318, 2024). "These genes include well annotated tumor-suppressor genes and oncogenes (e.g., TGFBR2 and MYC as well as genes that have never been previously linked to cancer in general, or to increased BC risk (including ADCY3, ATXN7, CFL1 and LPAR2)." (PMID 36991492, 2023). "As WDR1 enhances CFL1-mediated actin disassembly, the high expression of both WDR1 and CFL1 may synergistically disrupt cancer progression." (PMID 36875818, 2023). "While concrete evidence for the involvement of cofilin-1 in EV mediated metastasis of TNBC is extremely limited, there have been several studies suggesting that cofilin-1 mediates metastasis of other aggressive cancers." (PMID 34678587, 2022). "Therefore, the decrease in CFL1 expression after treatment of NJXA mainly destroyed the balance between F-actin and G-actin, which then further inhibited the cancer metastasis." (PMID 33791303, 2021). "Furthermore, we focused on the seven lncRNAs (PFKL, TPD52, ERGIC3, CFL1, CARS, IARS, and H19), which were related to cancer development." (PMID 32485786, 2020). "We found that MCL1, Cofilin1 (CFL1) and SRC mRNA were highly expressed by a wide range of these cancers, suggesting that a strategy of dual MCL-1 and SRC inhibition might be efficacious for many patients." (PMID 31735913, 2020). "In nude mice xenograft model silencing of CFL1 expression again correlates with inhibited cancer progression and lack of EMT markers." (PMID 29581975, 2018). "Based on the in-depth research of the CFL1 signaling pathway, blocking the EDG-1 signaling pathway may become an important strategy for the targeted therapy of malignant tumors." (PMID 29347944, 2018). "We regarded that CDC42, CFL1 and ADFP might promote the process of HBx-induced the inflammation and cancer in liver cells through dysregulation of cytoskeletal remodeling and lipid metabolism." (PMID 27708241, 2016). "Further studies that could evaluate co-localization and activity of cofilin-1 and EGFR in cancer cells would help to elucidate how exactly they are working together towards resistance behavior against cisplatin treatment." (PMID 25784483, 2015). "However, the mechanism of Cofilin 1 up-regulated in cancer cells was not presented in these studies." (PMID 30858759, 2019). "However, no report explains the relationship between CFL1 and PLD1 in cancer." (PMID 33784016, 2021).
infection (9 papers, 2015 to 2023). The state of being infected such as from the introduction of a foreign agent such as serum, vaccine, antigenic substance or organism. "Infection with SCV2, moreover, caused a downregulation in the protein cofilin-1, and impaired cell-cell adhesion, a finding that is recapitulated with infection with the spike protein." (PMID 37504520, 2023). "The spike infection in NHBE cells caused the loss of cofilin-1 protein (0.65-fold in Spike vs VSV-G, P = 0.0134)." (PMID 37504520, 2023). "LIMKi3, a LIM kinase 1 and 2 inhibitor, abrogated the phenotype and restored infection in both PBMCs and endocervix; inhibited E2-induced expression of total CFL1, pCFL1; and decreased pCFL1/CFL1 ratios." (PMID 35418661, 2022). "As the analysis was done either in uninfected or HIV-1BaL infected PBMCs, we cannot exclude effect of HIV-1BaL infection on CFL1 mRNA expression." (PMID 35418661, 2022). "LIMKi3 reverted the phenotype and restored infection levels; blocked E2‐induced increase in total CFL1 and pCFL1; and decreased the pCFL1/CFL1 ratios in PBMCs and endocervix." (PMID 35916394, 2022). "It is expected that myosins will also be involved in the trafficking of HSV-1 to the plasma membrane in neuronal cells as the actin cytoskeleton is modified by HSV-1 via cofilin-1 to facilitate its infection of neurons." (PMID 29473915, 2018). "Knockdown of CFL1 in PBMCs also abrogated the phenotype and partially restored infection." (PMID 35418661, 2022). "Cfl1 is able to hydrolyze xenobiotic as well as biological epoxides that might be encountered in the environment or during infection." (PMID 34235487, 2021). "During infection of neurons, HSV-1 causes a biphasic remodeling of the actin cytoskeleton by causing the inactivation of cofilin-1 followed by its subsequent activation, resulting in F-actin assembly and disassembly during early and late stages of infection, respectively." (PMID 29473915, 2018). "In an opposite manner compared to p-cofilin-1, the highest expression value for its activated counterpart was seen with PSP treatment before infection." (PMID 36992512, 2023). "We speculate that the detected increase in total CFL1, pCFL1 and increased pCFL1/CFL ratio in PBMCs and endocervix following E2 exposure may impair the dynamic cytoskeletal treadmill by locking CFL1 in inactivated state in HIV target cells, and therefore, provide protection against infection." (PMID 35418661, 2022).
adenocarcinoma (5 papers, 2011 to 2026). A common cancer characterized by the presence of malignant glandular cells. "CFL1 can promote actin, which is required for the formation of dendrites in the nuclei of adenocarcinoma and allows the exposure of the newly growing end of the F-actin at the outer periphery of the cell." (PMID 29347944, 2018). "Among them, two proteins (PKM2 and cofilin-1), significantly up-regulated in adenocarcinoma, were selected for detailed analysis." (PMID 22087286, 2011). "Clinically, high expression of both c-Myc and CFL1 genes correlated to worse survival rates among NSCLC patients, especially those with the adenocarcinoma subtype." (PMID 41888102, 2026).
neurodegenerative disease (5 papers, 2012 to 2024). A disorder of the central nervous system characterized by gradual and progressive loss of neural tissue and neurologic function. "Cofilin rods, which are primarily composed of actin and cofilin-1 and form in response to stressing conditions, have been suggested to be associated with neurodegenerative diseases such as AD by disrupting dendritic transportation and inducing synaptic dysfunction." (PMID 38212844, 2024). "Since hnRNP family proteins are known to be associated with neurodegenerative diseases, we hypothesized that hnRNP Q and hnRNP A1 could regulate the translation of Cfl1 mRNA." (PMID 34944075, 2021). "The disrupted interaction between cofilin-1 and PrP might cause the formation of actin rods, which leads to cellular transport deficits and synaptic dysfunction, as it is observed in other neurodegenerative diseases (reviewed in 14)." (PMID 23070823, 2012). "Therefore, nuclear translocation of CFL-1 may play an important role in degenerative diseases." (PMID 25689427, 2015).
neurological disorders (2 papers, 2023 to 2025). "These modules suggested the involvement of multiple novel genes for the first time including CFL1, GIT1, CDK5a, and CRMP2 and their signaling pathways which were related to the nervous system and neurological disorders including Eph‐ephrin signaling and semaphorin interactions." (PMID 41255384, 2025).
brain diseases (1 paper, 2021). "Moreover, other studies have indicated that cofilin-1 is a direct target for miR-107 in brain diseases." (PMID 33901009, 2021).